DLL4 (delta like canonical Notch ligand 4)
Diseases named in the same sentence as DLL4 in open-access papers (continued):
Sharing a sentence is not in itself a finding about the gene and the disease.
colon carcinoma (9 papers, 2008 to 2023). "More recently, anti-DLL4 was found to be active in a number of colon tumor xenografts including those harboring KRAS mutations which are insensitive to anti-EGFR treatment." (PMID 21831306, 2011). "The aims of this study were to characterise the in situ expression of Dll4 in colon cancer, to assess the association between Dll4 and established markers of hypoxia and angiogenesis and to determine the prognostic significance of these markers." (PMID 19844231, 2009). "The aim of this study was to characterise the expression of Dll4 in colon cancer and to assess whether it is associated with markers of hypoxia and prognosis." (PMID 19844231, 2009). "It was shown that endothelial cells induce CSC phenotype in colon cancer by producing Notch ligand Delta-like ligand 4 (DLL4)." (PMID 36810098, 2023). "In colon cancer, the combination of ionizing radiation and an anti-DLL4 antibody or a GSI dibenzazepine impaired tumor growth by promoting nonfunctional tumor angiogenesis and tumor necrosis." (PMID 34680255, 2021). "In human colon cancer xenografts, the Dll4 mAb can synergize the curative effect of ultrasound-stimulated microbubble and RT through a synergistic tumor growth delay of up to 24 days." (PMID 32742191, 2020). "In this work, we have investigated Dll4-blockade following combined ultrasound-microbubble and radiation-based vascular destruction in a highly aggressive and well-perfused colon cancer line." (PMID 24736631, 2014). "In this series of colon cancers, Dll4 expression was observed in the cytoplasm of the endothelium lining small vessels of neoplastic, but not normal tissue." (PMID 19844231, 2009). "In 71% (125 out of 175) of colon cancer tissues analysed, Dll4 expression was observed in the cytoplasm of the endothelial cells lining vessels adjacent to cancer." (PMID 19844231, 2009). "In all, 16% (28 out of 177) of colon cancers represented in the tissue microarrays expressed levels of Dll4 in the cytoplasm and membrane of neoplastic cells that approximated the intensity of expression observed in endothelium." (PMID 19844231, 2009). "This is the first study to perform a detailed evaluation of Dll4 expression in colon cancer, and to relate Dll4 expression to other known histological and prognostic markers." (PMID 19844231, 2009). "The positive association between endothelial Dll4 and epithelial VEGF in colon cancer, observed in this study, is also consistent with data from model systems in which Dll4 expression by endothelial cells is reported to be regulated by VEGF." (PMID 19844231, 2009). "Nevertheless, it is conceivable that manipulating Dll4–Notch signalling may have therapeutic relevance to colon cancer progression." (PMID 19844231, 2009). "In addition, Dll4 is expressed in some neoplastic cells with goblet cell differentiation, suggesting that Notch signalling can have a more direct role in colon cancer oncogenesis." (PMID 19844231, 2009). "The beneficial effect of combining anti-DLL4 and bispecific anti-DLL4/VEGF antibody with irinotecan was further confirmed in xenograft and orthotopic mouse models of gastric cancer and colon cancer." (PMID 34680255, 2021). "mRNA expression levels of NOTCH-1, NOTCH-3, NOTCH-4, JAG-1, DLL-4, Hes-1, and Hey-1 were quantified to elucidate the action of endostatin/CTX on the notch signaling pathway in colon cancer." (PMID 26762567, 2016). "Treatment of colon tumors with anti-DLL4 up-regulates markers of more differentiated colon cells (for example, ATOH1 and Chromogranin A) indicating that DLL4-Notch inhibition limits the stem/progenitor-like properties of colon tumor cells and promotes a more differentiated phenotype." (PMID 21831306, 2011). "Together, these data suggest that, in colon cancer, VEGF expression may be regulated by HIF-2 activity and the expression of VEGF may induce Dll4 expression in adjacent endothelial cells." (PMID 19844231, 2009).
colon carcinoma (continued). "The expression of Dll4 was observed preferentially in the endothelium of 71% (125 out of 175) of colon cancers, but not in the endothelium adjacent to normal mucosa (none out of 107, P<0.0001)." (PMID 19844231, 2009). "Moreover, targeting DLL4 looked like as an appealing strategy as an anti-DLL4 antibody was efficacious against both WT and mutant KRAS in combination with irinotecan, decreasing the population of colon cancer stem cells and promoting apoptosis in tumor cells both in vitro and in xenograft models." (PMID 34680255, 2021). "Moreover, the lack of a prognostic association for endothelial Dll4, a VEGF target, is in agreement with the lack of a prognostic association for VEGF in colon cancer in this study and elsewhere." (PMID 19844231, 2009).
diabetes (8 papers, 2021 to 2024). "Subsequently, a hyperglycemia-induced Dll4–Notch1-positive feedback loop has been recognized to contribute to pathogenic sustained Notch activation in diabetes." (PMID 34256844, 2021). "In previous studies, upregulated Jagged1 and DLL4 are accused to facilitate conditions associated with diabetes-induced vascular permeability such as diabetic retinopathy and diabetic macular edema." (PMID 34955884, 2021). "Dll4 with this extracellular domain induces disuse muscle atrophy and diabetes-induced muscle atrophy via Notch2." (PMID 38774645, 2024). "Even after accounting for potentially confounding variables such as gender, age, BMI, diabetes history, and systolic blood pressure, VE-cadherin, and DLL4 maintained a significant correlation with fistula immaturity." (PMID 39583102, 2024). "Previous studies have shown that Jag1 and Dll4 are secondary to increased hyperglycemia, activate the normative and non-normative Notch1 pathways, and destroy the endothelial adhesion connection in the retina in diabetes, which is consistent with our findings." (PMID 36533134, 2022). "Notably, the inhibition of Dll4‐Notch signaling was recently shown to drive differentiation of insulin‐producing cell progenitors, induce β‐cell proliferation and confer protection against streptozotocin‐induced diabetes." (PMID 35986504, 2022). "Furthermore, this activation of Notch2 by ECs-derived Dll4 is essential for the progression of muscle atrophy seen in these pathologies, suggesting that this secreted Dll4 may be a potential therapeutic target for disuse muscle and diabetes-induced muscle atrophy." (PMID 38774645, 2024). "We then examined the effect of the of duration of diabetes, SBP, HbA1c, and DLL4 (independent variables) on DR (dependent variable)." (PMID 34362349, 2021).
gastric cancer (8 papers, 2013 to 2022). A primary or metastatic malignant neoplasm involving the stomach. "The authors concluded that Dll4 is associated with gastric cancer progenitor cells, and its expression influences features linked to the Notch-1 pathway involving tumor formation, growth and development." (PMID 35406423, 2022). "In summary, DLL4 is associated with CSPCs in gastric cancer, and its expression impacts CSPC stemness characteristics associated with the Notch‐1 pathway including self‐renewal, differentiation, proliferation, chemoresistance, and tumor formation." (PMID 27891816, 2017). "In this study, we demonstrated that DLL4 overexpression associates with poor prognosis in gastric cancer by assessing tissue samples and patient survival." (PMID 27891816, 2017). "Interestingly, DLL4 and Nestin levels were tightly associated, suggesting DLL4 may affect GCSPCs through certain mechanisms in gastric cancer progression." (PMID 27891816, 2017). "In gastric cancer, high DLL4 levels reasonably resulted in hyperactivation of Notch1 signaling and were associated with poorer clinical outcome, stem-cell-like phenotype and 5-FU resistance." (PMID 34680255, 2021). "After DLL4 silencing in selected gastric cancer cell lines, the expression of GCSPC markers and colony formation ability were analyzed and the self‐renewal and differentiation capacities of the cells were evaluated." (PMID 27891816, 2017). "DLL4 expression was assessed in 383 human gastric cancer tissue samples by immunohistochemical staining." (PMID 27891816, 2017). "The correlation between DLL4 expression and the clinico‐pathological features of gastric cancer patients was then assessed." (PMID 27891816, 2017). "Our study provides a crucial supplement to the current knowledge of DLL4/Notch pathway in gastric cancer, and constitutes a potential reference for exploration and clinical therapy." (PMID 27891816, 2017). "To investigate the correlation between DLL4 expression and GCSPCs, we first measured DLL4 expression in four gastric cancer cell lines, including KATOIII, SGC7901, BGC823, and HGC27." (PMID 27891816, 2017). "In this study, DLL4 and Nestin levels were measured in 383 gastric cancer tissue samples by immunohistochemistry, and the clinico‐pathological features of patients assessed." (PMID 27891816, 2017). "Since this protein plays a key role in angiogenesis, future studies are required to determine if antiangiogenic therapy will be useful in DLL4-expressing gastric cancer." (PMID 23898884, 2013). "Both cancerous and stromal DLL4 expression were prognostic markers in gastric cancer as determined by univariate analysis." (PMID 23898884, 2013). "Overall surival of gastric cancer in the absence or presence of DLL4 expression were evaluated by univariate and multivariate analyses." (PMID 23898884, 2013). "Cancerous and stromal DLL4 expression was found in 48% and 22% in gastric cancer, and significantly affected postoperative clinical outcomes." (PMID 23898884, 2013). "Immunohistochemical staining showed DLL4 expression in cytoplasm of the four gastric cancer cell lines." (PMID 23898884, 2013). "DLL4 expression in gastric cancer cells and stroma was identified and evaluated immunohistochemically." (PMID 23898884, 2013). "Cell lysates extracted separately from the nucleus and cytoplasm in the gastric cancer cell lines were loaded and probed with anti-DLL4 antibody." (PMID 23898884, 2013). "DLL4 positivity in cancer cells and stroma was found in 88 (48%) and 41 (22%) of the 180 gastric cancer patients respectively." (PMID 23898884, 2013). "DLL4 expression was identified in the cellular membrane and cytoplasm of gastric cancer cells by immunoblotting and immunohistochemical staining." (PMID 23898884, 2013). "Furthermore, studies have indicated that the activation of Notch1, Notch4, and DLL4 is crucial in the initiation and progression of gastric cancer." (PMID 35846998, 2022).
gastric cancer (continued). "DLL4 protein expression was measured by western blotting in human gastric cancer cell lines." (PMID 35846998, 2022). "The results from gastric cancer studies have also confirmed that the invasion and metastatic abilities of gastric cancer cells are significantly enhanced after the upregulated expression of DLL4." (PMID 32742191, 2020). "Finally, the tumor formation ability of the gastric cancer cells was evaluated with different levels of DLL4 and multiple cell densities in vivo." (PMID 27891816, 2017). "In conclusions, cancerous and stromal DLL4 expression may be one of the angiogenesis-related prognostic markers in gastric cancer." (PMID 23898884, 2013). "Clinicopathologic features of DLL4-positive gastric cancers were assessed." (PMID 23898884, 2013). "We used immunohistochemistry to evaluate DLL4 expression of cancer cells and stroma in gastric cancer, speculating upon the clinical impact of this expression profile." (PMID 23898884, 2013). "Cancerous and stromal DLL4 expression may be an effective target of anti-DLL4 treatment in gastric cancer." (PMID 23898884, 2013). "Cancerous and stromal DLL4 expression may be a good target for anti-DLL4 therapy in gastric cancer." (PMID 23898884, 2013). "However, there is little published data examining DLL4 expression in gastric cancer." (PMID 23898884, 2013). "Another study involving 383 patients suffering from human gastric cancer (GC) were analyzed with their tissue samples immersed in immunohistochemical discoloration the appearance of Dll4 to determine the distinguished and undistinguishable gastric tumor stem cells." (PMID 35406423, 2022). "upregulation of Dll4 increases expression of MMP-2 and promotes progression of gastric cancer." (PMID 28881855, 2017). "DLL4 protein was identified in cytoplasm of the all gastric cancer cell lines, but not in the nucleus." (PMID 23898884, 2013). "Our findings demonstrate that DLL4 overexpression enhances CSPC self‐renewal, stimulating tumor proliferation, while restraining CSPC differentiation, which may lead to undifferentiated gastric cancer and a poor prognosis." (PMID 27891816, 2017). "The clinical significance of DLL4 expression in gastric cancer has not been clarified." (PMID 23898884, 2013).
Obesity (8 papers, 2019 to 2022). Accumulation of substantial excess body fat. "HFD causes the hypermethylation of MiR-30 genes via the activation of AMPK and delta-like ligand 4 (DLL4)-Notch signaling, leading to their downregulation and the exacerbation of inflammation and insulin resistance in an animal model of obesity." (PMID 34943849, 2021). "On the contrary, three genes involved in angiogenesis and one involved in energy homeostasis were up-regulated in thew SAT of individuals with normal weight compared to individuals with obesity; DLL4, PLIN2, VEGFA and PNPLA2." (PMID 33022994, 2020). "Interestingly, a HFD appears to contribute to DNA hyper-methylation of MiR-30 genes, leading to MiR-30 downregulation and promoting inflammation and insulin resistance in obesity via increased DLL4-Notch signaling." (PMID 33207733, 2020). "Together, these data indicate that blocking of CB1 in ATMs may contribute to improvement in obesity phenotype through miR-30e-5p regulation of DLL4." (PMID 31134094, 2019). "The family of 30 miRNAs has been recently reported to modulate metabolic inflammation through Notch signaling genes, including Delta-like ligand-4 (DLL4), which are elevated in obesity and serve as a form of communication between macrophages and adipocytes." (PMID 32366215, 2020). "Additionally, a direct correlation between BMI and gene expression was observed for AGER, ANGPT2, CD68, IFI30, NOTCH3 and SPP1, whereas an inverse correlation was achieved for DLL4, PLIN, PNPLA2 and VEGF (genes that were down-regulated due to obesity)." (PMID 33022994, 2020).
hepatocellular carcinoma (7 papers, 2016 to 2026). A malignant tumor that arises from hepatocytes. "Interestingly, recent studies showed that HBV X protein activated Notch signaling via Notch1/Notch4/Dll4 in HBV-associated hepatocellular carcinoma." (PMID 27800305, 2016). "The HBx protein also promotes survival of tumour through activation of DLL4-Notch1 in the context of HBV-related hepatocellular carcinoma." (PMID 41476776, 2026). "Moreover, the immunohistochemical (IHC) staining also shows that DLL4 expression is slightly decreased in human liver cirrhotic tissues and highly down-regulated in hepatocellular carcinoma (HCC) in comparison to normal liver tissue." (PMID 27542210, 2016). "In hepatocellular carcinoma, DLL4/Notch1 generally drives tumor growth, whereas Jag1/Notch2 tends to suppress tumor progression." (PMID 41588437, 2026).
lymph node metastasis (7 papers, 2013 to 2022). "Fascinatingly, positive Dll4 appearance was meaningly related to improved lymph node metastasis and distal metastasis danger as likened with patients presenting adverse Dll4 appearance." (PMID 35406423, 2022). "Moreover, gene DLL4 is closely related to lymph node metastasis and was found to be an independent predictor of lymph node metastasis of PTC." (PMID 31126066, 2019). "In our study, DLL4-positive cancer had more lymph node metastases and severe lymphatic invasion." (PMID 23898884, 2013). "Interestingly, positive DLL4 expression was significantly associated with increased lymph node metastasis and distal metastasis risk as compared with patients showing negative DLL4 expression." (PMID 27891816, 2017). "The results suggest that the expression of ECM2, PCDH12, EPAS1, CD93, DLL4, and ARHGEF15 are significantly different in age, N (lymph node metastasis status), and whether radiotherapy is received or not." (PMID 35953532, 2022).
adenoma (6 papers, 2009 to 2025). A neoplasm arising from the epithelium. "IF staining revealed that Jag1 and Dll4 were present at comparable levels, and localized as expected at the membrane of both normal organoids and adenoma-derived spheroids." (PMID 30065304, 2018). "In the present study, Dll4 and Jagged1 ligands appear to be the Notch pathway components with greater expression in the small and large ApcMin/+ adenomas." (PMID 28086833, 2017). "In the whole sections of colorectal adenomas with adjacent adenocarcinoma, Dll4 was observed at identical frequencies in the endothelium found in both the adenomas and adenocarcinomas (12 out of 12)." (PMID 19844231, 2009). "Instead, it has been described that other ligands, such as Dll1 and Dll4, were underexpressed in non functioning and prolactin secreting adenomas, and overexpressed in corticotropinomas respectively, pointing to a specific Notch system profile for different pituitary adenomas histotypes." (PMID 28915655, 2017). "The observation that adenoma initiation in the ApcMin/+ intestines required Jag1-induced Notch signaling suggested that either Jag1 was the only Notch ligand expressed in the adenomas, or adenoma-specific Notch1 was refractory to the induction by other ligands such as Dll4." (PMID 30065304, 2018). "Similar findings were made with respect to DLL1 and DLL4 expression, which was significantly increased in FAP duodenal tissue, with the highest expression in FAP adenomas, while only DLL4 correlated significantly with IL-17A(+)NKp44(−)ILC3 frequency." (PMID 40280932, 2025). "Comparatively, in adenomas, ≥2-fold Notch3 expression was detected in 56% followed by Notch1 (44%), Notch4 (33%), and Notch2 (11%), while for ligand Jag1, mRNA was overexpressed in 33%, Jag2, Dll1, and Dll3 in 11%, whereas Dll4 was not expressed in adenomas." (PMID 32211044, 2020).
Hyperglycemia (6 papers, 2021 to 2025). An increased concentration of glucose in the blood. "In diabetic vascular complications, the γ-secretase target notch receptor 3 (NOTCH3) and its ligand delta-like canonical Notch ligand 4 (DLL4) are central mediators of vascular basement membrane thickening, influenced by hyperglycemia and inflammatory factors." (PMID 41359105, 2025). "Administration of anti-DLL4 Ab in T1D mice controls hyperglycemia over time and improves the glucose tolerance test (GTT)." (PMID 34881246, 2021). "The Dll4-Notch1 loop induced by hyperglycemia impairs wound healing." (PMID 38448482, 2024).
ischemia (6 papers, 2012 to 2024). A hypoperfusion of the BLOOD through an organ or tissue caused by a PATHOLOGIC CONSTRICTION or obstruction of its BLOOD VESSELS, or an absence of BLOOD CIRCULATION. "Similarly, inhibition of DLL4 signaling by intramuscular injection of an adenovirus encoding a soluble form of DLL4 extracellular domain impairs reparative angiogenesis in a mouse model of ischemia." (PMID 22487493, 2012). "Dll4 expression was upregulated in Plxnd1iECKO mice, which demonstrated that the absence of Plexin-D1 causes aberrant activation of VEGF signaling in vessel remodeling post-ischemia." (PMID 33978913, 2022). "Besides, Dll4-Notch signaling determines the de novo formation of arterial collateral networks and arterial function in mouse ischemia models." (PMID 33473260, 2020).